ALDH2 (aldehyde dehydrogenase 2 family member)
Diseases named in the same sentence as ALDH2 in open-access papers (continued):
Sharing a sentence is not in itself a finding about the gene and the disease.
hypothyroidism (2 papers, 2021 to 2025). Abnormally low levels of thyroid hormone. "In addition, the expression of Ehhadh, Haao, and Cyp1A2 were up-regulated and Cat, Aldh2, and Ehhadh were down-regulated in hypothyroidism rats." (PMID 33959028, 2021). "For example, genetically predicted plasma levels of ALDH2, BCL2L15, WASL, POLR2F, and ADPGK were positively associated with hypothyroidism risk, while H2BC21 and H2BC26 showed negative associations." (PMID 40868097, 2025).
injury (2 papers, 2017 to 2025). Damage inflicted on the body as the direct or indirect result of an external force, with or without disruption of structural continuity. "Similarly, pharmacological activation of ALDH2 can rescue heatstroke-induced acute lung injury by alleviating oxidative stress and decreasing endothelial cell apoptosis." (PMID 40968356, 2025). "Additionally, ALDH2 can be modified by succinylation at K385, leading to a notable decrease in ALDH2 activity and aggravation of acetaminophen-induced liver injury in a mouse model." (PMID 40968356, 2025).
mental disorder (2 papers, 2023 to 2025). A disease that has its basis in the disruption of mental process. "Thus, these ORs are far larger than for a typical GWAS finding in psychiatric disease – the risk effect being comparable to the effects of the functional ALDH2 and ADH1B variants on AUD and alcohol drinking." (PMID 41510264, 2025).
myelodysplastic syndrome (2 papers, 2021 to 2023). A clonal hematopoietic disorder characterized by dysplasia and ineffective hematopoiesis in one or more of the hematopoietic cell lines. "Strikingly, when FA patients carry the homozygous ALDH2 variant (AA genotype), they invariably display a severe phenotype immediately after birth, such as hypoplastic anemia as well as myelodysplastic syndrome (MDS), reflecting loss of hematopoietic stem cells or accumulating mutations." (PMID 36345163, 2023). "Similar abnormalities were observed in bone marrow-MSCs from patients suffering from myelodysplastic syndrome (MDS), suggesting a role of pesticide-induced ALDH2 inhibition in the pathophysiology of this pre-leukemic disease." (PMID 34830855, 2021).
opioid use disorder (2 papers, 2022 to 2024). A substance-related disorder that involves the recurring use of opioids despite negative consequences. "ALDH2 is an important factor in opioid-use disorder and is associated with neuropsychological performance after methadone maintenance therapy." (PMID 38448893, 2024). "The authors suggested that the ADH1B*1/*1, ADH1B*1/*2, and ALDH2*1/*1 genotypes may interact and guard their carriers against opioid use disorder, and the protective effect may vary relative to DRD2 gene polymorphisms." (PMID 35743793, 2022). "Moreover, particular combinations of the dopamine D2 gene and the ALDH2 gene polymorphisms seem to be protective against AUD and opioid use disorder." (PMID 35743793, 2022).
Osteopenia (2 papers, 2014 to 2023). Osteopenia is a term to define bone density that is not normal but also not as low as osteoporosis. "We hypothesized that AAVrh.10hALDH2 administration after establishment of osteopenia would be able to reverse bone loss due to ALDH2 deficiency and chronic ethanol consumption." (PMID 37065630, 2023). "ALDH2*2 Tg mice exhibited small body size, muscle atrophy, decreased fat content, osteopenia, and kyphosis, accompanied by increased muscular 4-HNE levels." (PMID 25305781, 2014).
periodontitis (2 papers, 2016 to 2021). An acute or chronic inflammatory process that affects the tissues that surround and support the teeth. "To mimic dental bacterial infection, we compared the dental bony defects in wild-type mice and ALDH2*2 knockin mice after injection with purified lipopolysaccharides (LPS), derived from P. gingivalis which is a bacterial species known to cause periodontitis." (PMID 33925003, 2021). "We believe that these results are important for periodontitis and warrant confirmation by epidemiological and clinical studies in human populations where ALDH2*2 mutation, alcohol drinking, and poor oral hygiene are common." (PMID 33925003, 2021). "However, to evaluate the association of polymorphism of ALDH2 genotypes with presence of periodontitis after adjustment for drinking status, a future study is necessary." (PMID 27557802, 2016). "However, the mechanism linking ALDH2 deficiency and bone loss in periodontitis is still not clear." (PMID 33925003, 2021).
pharyngeal cancers (2 papers, 2023 to 2024). "ALDH2 dysfunction has been widely linked to an increased risk of alcohol-related cancers, and individuals carrying the ALDH2*2 allele may face a 10-fold increased risk of developing upper esophageal and pharyngeal cancers with chronic alcohol intake." (PMID 36831600, 2023).
sarcoma (2 papers, 2018 to 2024). A usually aggressive malignant neoplasm of the soft tissue or bone. "CHKB-DT was shown to physically interact with the mRNA of ALDH2 and fused in sarcoma (FUS) through the GGUG motif." (PMID 39465137, 2024).
Ventricular arrhythmia (2 papers, 2021 to 2023). "A common variant in the aldehyde dehydrogenase, ALDH2, which is enriched in East Asian populations can promote the risk of ventricular arrhythmia in mice exposed to a low alcohol dose emulating light alcohol consumption in humans." (PMID 37280327, 2023). "By programmed electrical stimulation, rotors are only provokable in EtOH-treated ALDH2*2 KI mice along with higher number and duration of ventricular arrhythmia episodes." (PMID 37280327, 2023).
abdominal aortic aneurysm (1 paper, 2025). Enlargement and ballooning of the vessel that supplies arterial blood to the abdomen, pelvis and legs. "In abdominal aortic aneurysm (AAA), ALDH2 inhibits aneurysm formation by inhibiting ROS production, reducing vascular inflammation, and attenuating vascular smooth muscle cell apoptosis, suggesting that ALDH2 can serve as a novel treatment option for AAA." (PMID 40968356, 2025).
acute pancreatitis (1 paper, 2020). An acute inflammatory process that leads to necrosis of the pancreatic parenchyma. "A comprehensive systematic review and meta‐analysis of the genetic evidence for acute pancreatitis was conducted, and identified credible associations of SPINK1, ALDH2, IL1B, IL6 and IL18 with the risk of acute pancreatitis." (PMID 32011822, 2020).
amyotrophic lateral sclerosis (1 paper, 2024). Amyotrophic lateral sclerosis (ALS) is a neurodegenerative disease characterized by progressive muscular paralysis reflecting degeneration of motor neurons in the primary motor cortex, corticospinal tracts, brainstem and spinal cord. "The study aims to investigate the effects of the ALDH2 rs671 (A) allele and high sensitivity C-reactive protein (hs-CRP) on the clinical phenotypes of amyotrophic lateral sclerosis (ALS) in male and female patients." (PMID 39290715, 2024).
arteriosclerosis (1 paper, 2023). A vascular disorder characterized by thickening and hardening of the walls of the arteries. "The proportion of ALDH2 rs671 A allele in patients with arteriosclerosis in multiple arteries was significantly higher than that in patients with arteriosclerosis in single artery (35.6% vs. 30.9%, P = 0.038)." (PMID 37355582, 2023). "The possible association of the ALDH2 genotypes with potential risk factors for arteriosclerosis in multiple arteries based on three genetic modes of inheritance: co-dominant model, dominant model, and recessive model." (PMID 37355582, 2023). "ALDH2 rs671 A/A genotype may be an independent risk factor for arteriosclerosis in multiple arteries." (PMID 37355582, 2023). "The frequencies of ALDH2 rs671 and MTHFR rs1801133 genotypes and alleles were compared between the arteriosclerosis in single artery and arteriosclerosis in multiple arteries groups." (PMID 37355582, 2023). "The relationship between ALDH2 rs671 and MTHFR rs1801133 polymorphisms and arteriosclerosis in single artery and arteriosclerosis in multiple arteries was analyzed." (PMID 37355582, 2023). "But the result of the relationship of ALDH2 and MTHFR gene polymorphisms and arteriosclerosis in multiple arteries is still unclear." (PMID 37355582, 2023). "In summary, the relationship between ALDH2 rs671 and MTHFR rs1801133 polymorphisms and arteriosclerosis in multiple arteries was identified in a cohort study." (PMID 37355582, 2023). "In the current study, we evaluated the association between ALDH2 rs671, MTHFR rs1801133 polymorphisms and arteriosclerosis in single artery and arteriosclerosis in multiple arteries." (PMID 37355582, 2023). "Second, this study only analyzed the relationship between the common polymorphisms of ALDH2 and MTHFR genes and the risk of arteriosclerosis in multiple arteries." (PMID 37355582, 2023). "The result of the relationship of ALDH2 and MTHFR gene polymorphisms and arteriosclerosis in multiple arteries is still unclear." (PMID 37355582, 2023). "So, future studies that include larger sample sizes, the degree of arteriosclerosis, the analysis of the full-length variation of ALDH2 and MTHFR genes, and analysis of folic acid levels are needed." (PMID 37355582, 2023). "The distributions of ALDH2 rs671 genotypes in patients with arteriosclerosis in single artery (χ2 = 0.492, P = 0.483) and patients with arteriosclerosis in multiple arteries (χ2 = 1.551, P = 0.213) were consistent with Hardy-Weinberg equilibrium, respectively." (PMID 37355582, 2023). "The purpose was to investigate the relationship of ALDH2 and MTHFR gene polymorphisms with arteriosclerosis in multiple arteries." (PMID 37355582, 2023). "The χ2 test was used to test the significance of the Hardy-Weinberg equilibrium of the ALDH2 rs671 and MTHFR rs1801133 polymorphisms in the patients with arteriosclerosis in single artery and arteriosclerosis in multiple arteries." (PMID 37355582, 2023). "Our study found that ALDH2 rs671 A/A and MTHFR rs1801133 T/T genotypes may be independent risk factors for arteriosclerosis in multiple arteries." (PMID 37355582, 2023). "The results of this study show that ALDH2 rs671 A/A and MTHFR rs1801133 T/T genotypes may be independent risk factors for arteriosclerosis in multiple arteries." (PMID 37355582, 2023). "In the perspective of mechanism, ALDH2 plays an important role in the development and progression of arteriosclerosis by inhibiting oxidative low-density lipoprotein (ox-LDL)-induced foam cell formation via suppressing CD36 (cluster of differentiation 36) expression." (PMID 37355582, 2023). "ALDH2 rs671 A/A and MTHFR rs1801133 T/T genotypes may be independent risk factors for arteriosclerosis in multiple arteries." (PMID 37355582, 2023).
arteriosclerosis (continued). "The proportion of ALDH2 rs671 A allele (35.6% vs. 30.9%, P = 0.038) and MTHFR rs1801133 T allele (32.6% vs. 27.1%, P = 0.012) in patients with arteriosclerosis in multiple arteries was significantly higher than that in arteriosclerosis in single artery, respectively." (PMID 37355582, 2023). "Acetaldehyde dehydrogenase 2 (ALDH2) and methylenetetrahydrofolate reductase (MTHFR) play an important role in the pathogenesis of arteriosclerosis by participating in the oxidation and reduction reactions in vascular endothelial cells." (PMID 37355582, 2023). "First, no information was collected about the degree or grade of arteriosclerosis of the subjects, which limited the analysis of the relationship between ALDH2 rs671 and MTHFR rs1801133 and the degree or grade of arteriosclerosis." (PMID 37355582, 2023).
Brain atrophy (1 paper, 2015). Partial or complete wasting (loss) of brain tissue that was once present. "There was also evidence of brain atrophy in these mice; measurements of the area of hippocampal formation and overlying neocortex indicated a 15% reduction in area in Aldh2-/- mice." (PMID 25910195, 2015).
cardiopulmonary disease (1 paper, 2022). "Although ALDH2 has been shown to have essential roles in the development of cardiopulmonary disease in both experimental and clinical backgrounds, little is known regarding its role in PH, right ventricular remodeling, and the underlying autophagy-dependent mechanisms." (PMID 35770049, 2022).
cerebrovascular diseases (1 paper, 2020). "ALDH2 has emerged in recent years as a crucial guardian against several stressor or toxic insults, supporting its potential role in many diseases, including cardiovascular and cerebrovascular diseases that are linked to ageing." (PMID 31947800, 2020).
Cis (1 paper, 2023). "Consistent with the results of renal function, KIM-1 was increased in Cis-AKI mice and to a higher level in ALDH2 KO Cis-AKI mice." (PMID 36670098, 2023).
colitis (1 paper, 2024). Inflammation of the colon. "Our result of reduced ALDH2 in colitis could potentially be explained by the reduced presence of the ALDH+ macrophage and dendritic cells in the colon of UC, considering that inflammatory myeloid cells are largely recruited to the lamina propria in UC." (PMID 38668322, 2024).
colorectal adenoma (1 paper, 2023). An adenoma that arises from the colon or rectum. "In addition, a case–control study in Japan found no consistent connection between MTHFR C677T and ALDH2 polymorphisms and colorectal adenoma, while the mutant 677T allele was associated with a reduced disease risk." (PMID 38202226, 2023).
complication (1 paper, 2016). Any disease or disorder that occurs during the course of, or because of, another disease, treatment, or procedure. "Our study implicates individuals with compromised ALDH2 activity may have higher propensity to develop diabetic cardiac complications or increase the severity of the damage." (PMID 27882330, 2016).
coronary artery spasms (1 paper, 2024). "Individuals who carry the aldehyde dehydrogenase 2 (ALDH2)*2, which is associated with deficient ALDH2 activity, are also at a higher risk of coronary artery spasms." (PMID 39452475, 2024).
coronary atherosclerosis (1 paper, 2026). Atherosclerosis of the coronary vasculature. "The relationship between ALDH2 rs671 polymorphism and coronary atherosclerosis risk was analyzed." (PMID 41948587, 2026). "Aldehyde dehydrogenase 2 (ALDH2) is an important enzyme for the oxidation metabolism of aldehyde substances, and it is related to coronary atherosclerosis." (PMID 41948587, 2026).
cystitis (1 paper, 2021). Inflammation of the urinary bladder. "Compelling evidence indicate that ALDH2 gene alleviates ketamine-induced cystitis in mouse model through inhibiting oxidative stress." (PMID 34362382, 2021). "It has been reported that ALDH2 knock-out mice exhibits significantly enhanced oxidative stress and inflammation in ketamine-induced cystitis." (PMID 34362382, 2021).
dermatitis (1 paper, 2023). An inflammatory process affecting the skin. "Since many Oriental people have genetically reduced acetaldehyde dehydrogenase type 2 (ALDH2) activity, ethanol disinfection causes acetaldehyde to accumulate in the skin, resulting in dermatitis." (PMID 38239994, 2023).
endometrial cancer (1 paper, 2023). Primary or metastatic malignant neoplasm involving the endometrium (mucous membrane that lines the endometrial cavity). "The incorporation of RTN4, LAMP2, WDR1, KRT13, ALDH2 and ILF3 gave rise to a ten-marker biomarker panel, which predicted endometrial cancer with an AUC of 0.91 (0.86–0.96), and was the best performing diagnostic model." (PMID 36807337, 2023).
endometriosis (1 paper, 2021). The growth of functional endometrial tissue in anatomic sites outside the uterine body. "Increasing the ALDH2 activity through Alda-1 was found to diminish endometriosis lesion formation and further reduce pain in rodents." (PMID 34680034, 2021). "Modulating the ALDH2 activity may thus also benefit patients suffering from endometriosis." (PMID 34680034, 2021).
endotoxemia (1 paper, 2024). "We hypothesized that binge EtOH exposure causes greater brain damage in Aldh2-KO mice compared to their WT counterparts through elevated gut leakiness and endotoxemia." (PMID 38891060, 2024). "Binge alcohol decreased intestinal tight/adherens junction proteins but increased oxidative stress-mediated post-translational modifications (PTMs) and enterocyte apoptosis, leading to elevated gut leakiness and endotoxemia in Aldh2-KO mice compared to corresponding WT mice." (PMID 38891060, 2024).
glaucoma (1 paper, 2020). Increased pressure in the eyeball due to obstruction of the outflow of aqueous humor. "Our data suggest that glaucoma patients should avoid excessive alcohol consumption regardless of ALDH2 polymorphism." (PMID 33060820, 2020).
Graves ophthalmopathy (1 paper, 2025). An autoimmune disorder of the EYE, occurring in patients with Graves disease. "Anti-ALDH2 antibodies also served as biomarkers for Graves’ ophthalmopathy progression." (PMID 40868097, 2025).
H1N1 influenza (1 paper, 2017). "WT and Aldh2−/− mice were infected with H1N1 influenza through the nose and lungs were collected after 8 days." (PMID 28431562, 2017).
hippocampal atrophy (1 paper, 2024). "Our study is the first to demonstrate that the ALDH2 rs671 variant is associated with MCI, independent of alcohol consumption, hippocampal atrophy, and small vessel dysfunction." (PMID 39401906, 2024). "For the first time, our study findings suggest that the ALDH2 rs671 variant is a mild risk factor for MCI, independent of alcohol use, hippocampal atrophy, and cerebral small vessel dysfunction, using a cross-sectional approach with a Japanese Brain MRI Checkup Cohort database." (PMID 39401906, 2024).
Hyperinsulinemia (1 paper, 2016). An increased concentration of insulin in the blood. "ALDH2-offered protection was recapitulated by the use of its agonist Alda-1, supporting the therapeutic potential of this enzyme in hyperinsulinemia." (PMID 27634872, 2016).
invasive breast carcinoma (1 paper, 2023). A carcinoma that infiltrates the breast parenchyma. "We also examined known variants and proxies with r2 ≥ 0.8 in four alcohol metabolism gene regions (ADH, CYP2E1, ALDH1, and ALDH2) in our meta-analysis results for main genetic effects on invasive breast cancer." (PMID 37308906, 2023).
kidney (1 paper, 2023). "This suggested that Epimedium fried with suet oil could promote the expression of ALDH2, improve the body’s energy metabolism, and then improve the state of kidney Yang deficiency." (PMID 36762111, 2023).
kidney transplantation (1 paper, 2025). "Our present findings showed that ALDH2 was negatively correlated with the MAPK signaling pathway in kidney transplantation AKI, demonstrating that ALDH2 is also able to inhibit the activation of the MAPK signaling pathway in kidney transplantation AKI." (PMID 40103812, 2025).
left ventricular hypertrophy (1 paper, 2022). Enlargement of the LEFT VENTRICLE of the heart. "Deficiency of ALDH2 (ALDH2-/-) significantly reduced EF and FS as comparedwith WT mice 12 weeks post 5/6 NX, while left ventricular hypertrophy was similarbetween the two NX groups." (PMID 39076225, 2022). "Our data indicated that ALDH2 deficiency did notaffect NX-induced left ventricular hypertrophy, but could increase oxidativestress and exacerbate CKD-induced cardiac dysfunction, partly via downregulationof UCP2 and Nrf2/ARE (antioxidant response element) pathways." (PMID 39076225, 2022). "These resultssuggested that ALDH2 deficiency could exacerbate CKD-induced cardiac dysfunction,but did not affect left ventricular hypertrophy; left ventricular hypertrophy wasobserved only in WT with CKD group." (PMID 39076225, 2022).
lumbar disc herniation (1 paper, 2018). "However, little information is found about the association between ALDH2 polymorphisms and lumbar disc herniation (LDH) in Chinese Han population." (PMID 30166580, 2018).
lymphoma (1 paper, 2023). A malignant (clonal) proliferation of B- lymphocytes or T- lymphocytes which involves the lymph nodes, bone marrow and/or extranodal sites. "No expression difference was found of ALDH2, ANGPTL4, BPGM, and PAM between lymphoma patients and control samples." (PMID 36755971, 2023).